CYP1B1 (cytochrome P450 family 1 subfamily B member 1)
Diseases named in the same sentence as CYP1B1 in open-access papers (continued):
Sharing a sentence is not in itself a finding about the gene and the disease.
breast carcinoma (continued). "ZNF276 can promote the malignant phenotype of breast cancer by activating the CYP1B1-mediated Wnt/β-catenin pathway." (PMID 37143720, 2023). "To explore the possible clinical significance of CYP1B1 expression in breast cancer and CL breast cancer, we analyzed the UNC337 Microarray Database." (PMID 36077068, 2022). "Fenofibrate induces apoptosis of triple-negative breast cancer cells via activation of the NF-κB pathway, and Wy14643 shows toxicity to breast cancer cells via PPARα–CYP1B1 expression, suggesting the therapy potential of PPARα in breast cancer." (PMID 36589809, 2022). "It has been reported that the expression of CYP1B1 is significantly increased in hormone-related cancers, including breast cancer, endometrial cancer, ovarian cancer, and PCa." (PMID 35292057, 2022). "The results of the current study, while compelling, are limited in that they rely on the manipulation of CYP1B1 levels in a subset of breast cancer cell lines." (PMID 36077068, 2022). "CYP1B1 is abnormally highly expressed in a variety of cancers (e.g., breast cancer, head and neck cancer, and PCa), and its effect on reducing the drug sensitivity of tumor cells has been widely reported." (PMID 35292057, 2022). "Analysis of CYP1B1 expression by previously assigned intrinsic breast cancer subtypes showed significantly higher expression in the CL subtype and significantly lower expression in the luminal B subtype." (PMID 36077068, 2022). "Taken together, these results demonstrated that CYP1B1 is the functional target of ZNF276 in breast cancer." (PMID 36085146, 2022). "Wound healing and transwell migration and invasion assays revealed that the overexpression CYP1B1 increased breast cancer migration and invasion." (PMID 36428734, 2022). "The expression of CYP1B1 in tumor tissues was considerably higher than that in normal tissues, especially in hormone-related cancers, such as breast cancer, ovarian cancer, glioma and prostatic cancer." (PMID 36085146, 2022). "ZNF276 recruits MAGEB2 to facilitate the transcription of CYP1B1 and the activation of the Wnt/β-catenin pathway, leading to a malignant breast cancer phenotype." (PMID 36085146, 2022). "Early studies of breast cancer cell lines report that aryl hydrocarbon receptor (AHR)-mediated induction of CYP1B1 is higher in cells having a mesenchymal morphology." (PMID 36077068, 2022). "Continuous research has shown that CYP1B1 is related to tumor drug resistance, laying the foundation for CYP1B1 as a new target for reversing breast cancer neoadjuvant chemotherapy drugs resistance." (PMID 34502549, 2021). "As well, age at breast cancer diagnosis was correlated with GSTM1 and GSTT1 genotypes, together with other polymorphisms in the estrogen metabolic pathway, namely with CYP1B1 Val432Leu and MTHFR C677T polymorphisms." (PMID 33513690, 2021). "In this study, univariate logistic regression analysis showed that CYP1A1, CYP1B1, and SULT1A1 gene polymorphisms are closely related to the occurrence of breast cancer." (PMID 33632172, 2021). "LNC942 directly recruited METTL14 protein through specific recognition sites, thus enhancing the expression of downstream target genes CXCR4 and CYP1B1 and promoting breast cancer cell proliferation." (PMID 34336856, 2021). "LINC00942 was reported to promote METT14-mediated M6A methylation and regulate the expression and stability of its target gene CXCR4 and CYP1B1 during the initiation and progression of breast cancer." (PMID 34760693, 2021). "This is in concordance with a few other reports which indicated that CYP1B1 4326 G allele was associated with a lower response rate, progressive free survival rate (PFS) and decreased overall survival in breast cancer patients treated with taxanes." (PMID 33906328, 2021). "In breast cancer cell development, cytochrome P450 1B1 (CYP1B1) plays a vital role by activating environmental carcinogens and endogenous estrogens." (PMID 34336089, 2021).
breast carcinoma (continued). "Metformin, a medication usually given to treat diabetes, has also been shown to inhibit CYP1B1 expression, specifically in breast cancer cells." (PMID 33185690, 2020). "Specifically, the inflammatory cytokine interleukin-6 (IL-6) has been shown to induce CYP1B1 via miR27b in colorectal and breast cancer cells." (PMID 33185690, 2020). "Although Cyp1b1 has been reported to promote breast cancer metastasis 22, more functional validation both in vitro and in vivo is still required." (PMID 32792858, 2020). "Leptin and prostaglandin E2 have also been shown to up-regulate CYP1B1 expression through ligand-independent activation of the ERα pathway in MCF-7 breast cancer cells." (PMID 33185690, 2020). "To illustrate this point in cancer cells here, we generated CYP1B1 knockout SUM149 inflammatory breast cancer cells and quantified AHR activity in the presence or absence of AHR agonists using an AHR-driven (pGudLuc) reporter construct." (PMID 33396563, 2020). "For instance, immunohistochemistry reports showed high CYP1B1 mRNA and protein levels in prostate tumors, mammary tumors and peritumor benign tissues, and ovarian cancer tissues." (PMID 33185690, 2020). "Collectively, these findings suggest that AHR and GPER are involved in the CYP1B1 and cyclin D1 induction upon exposure to 3MC toward the growth responses observed in breast cancer cells and CAFs." (PMID 31370872, 2019). "Human cytochrome P450 1B1 (CYP1B1)-mediated biotransformation of endobiotics and xenobiotics plays an important role in the progression of human breast cancer." (PMID 31775380, 2019). "In the present study, WY-14643 strongly induced transcriptional activation of CYP1B1 in MCF-7 breast cancer cells." (PMID 31775380, 2019). "Because CYP1B1 is mainly regulated by ERE in breast cancer, we assumed that WY-14643 directly or indirectly affects this transcription factor." (PMID 31775380, 2019). "In this study, we investigated the effect of the PPARα agonist, WY-14643, on CYP1B1 expression and the related mechanism in breast cancer cells." (PMID 31775380, 2019). "We also measured the expression of CYP1B1 gene in another breast cancer cell line, MDA-MB-231 by WY1234 treatment." (PMID 31775380, 2019). "After adjustment for multiple testing, this study showed statistically significant interactions between rs1056827 in CYP1B1, rs2959008 and rs7173655 in CYP11A1, the deletion of GSTT1, and rs1052133 in hOGG1 and acrylamide intake for ER+ breast cancer risk." (PMID 29445914, 2019). "Based on these observations, inhibition of CYP1B1, an important drug target, has been proposed as a therapeutic strategy for breast cancer." (PMID 31775380, 2019). "Several compounds like aromatic hydrocarbons as well as estrogens can stimulate the expression of the AHR target gene CYP1B1, which is overexpressed in a variety of tumors including breast cancer." (PMID 31370872, 2019). "Leptin has been suggested to induce CYP1B1 expression in ERα-positive breast cancer cells in a mechanism that involves AKT and ERK signaling pathways." (PMID 31380268, 2019). "CYP1B1 is presumed to be essential for the initiation and development of various hormone-dependent tumors, including breast cancer, through the biotransformation of endogenous estrogens and environmental carcinogens." (PMID 31775380, 2019). "In 2015, Dumont and his colleagues proposed that the genotypes of ERCC1 rs11615 and CYP1B1 rs1056836 can jointly predict the prognosis responses to neoadjuvant chemotherapy of breast cancer patients, especially ER positive ones." (PMID 30096175, 2018). "For example, genetic polymorphisms of CYP1B1 and ABCB1 are associated with the clinical response to chemotherapy in breast cancer." (PMID 28085094, 2017). "Differently, in breast cancer, CYP1A1 regulates proliferation and survival of tumor cells, while CYP1B1 indirectly causes the generation of free radicals." (PMID 29657291, 2017).
breast carcinoma (continued). "In accordance with our findings, it has been recently reported that G-1 is also able to up-regulate the expression of both AhR and CYP1B1 in ER-positive MCF-7 breast cancer cells, although the molecular mechanisms involved remain to be elucidated." (PMID 29290975, 2017). "E2 and its hydroxylated metabolites resulting from CYP1B1 and CYP1A1 have been implicated in breast cancer." (PMID 28212313, 2017). "Estrogen-CYP1B1 landscape via GPER should be taken into account in setting novel pharmacological approaches targeting breast cancer development." (PMID 29290975, 2017). "In this scenario, it is worth mentioning that CYP1B1 expression is triggered by estrogens through the estrogen receptor (ER)α in breast cancer cells." (PMID 29290975, 2017). "Consistent up-regulation of CYP1B1 in breast cancers suggests that this enzyme plays an important role in cancer, potentially by influencing cell migration." (PMID 26984638, 2016). "In human breast cancer cell lines, higher CYP1B1 expression over CYP1A1 has been related to higher AhR expression and ERα-negative status." (PMID 26715507, 2015). "In conclusion, BRCA1 (Pro871Leu), ERCC1 (Asn118Asn), CYP1B1 (Leu432Val), and SLCO1B3 (rs11045585) are associated with response to NCT in our cohort of breast cancer patients." (PMID 26180747, 2015). "Many studies have evaluated the association between SNPs in estrogen-related genes, such as CYP17, CYP19, CYP1A1, CYP1B1, COMT, GSTP1, and ERα/β, and the risk of breast cancer, especially in postmenopausal women." (PMID 25689428, 2015). "Turning to markers of AhR activation, we measured increased Cyp1b1 in adjacent mammary gland and mammary tumors of DMBA-treated animals." (PMID 26715507, 2015). "Conversely, Cyp1b1 levels were markedly increased, on average ~5.0 and 14.0-fold of control, respectively in peritumoral tissue and mammary tumors." (PMID 26715507, 2015). "Fourthly, in breast cancer cells, TCDD induces the expression of CYP1A1 and CYP1B1, which encode enzymes that convert E2 into catecholestrogens." (PMID 25257533, 2014). "In addition, CYP1B1 catalyzes the 4-hydroxylation of estradiol to generate 4-hydroxy estradiol, a catechol metabolite that produces free radicals, causes cellular damage, and is associated with carcinogenic activity of estrogen and the development of breast cancer." (PMID 22761658, 2012). "Further, the level of miR-27b was shown to be inversely correlated with the expression of CYP1B1 in breast cancer tissue." (PMID 22114726, 2011). "Human studies have suggested that high-activity CYP1B1 alleles and low-activity COMT alleles are associated with increased risk of breast cancer and other E2-responsive cancers." (PMID 20435547, 2010). "Nevertheless, our results are consistent with recent findings from in vitro and animal experiments implicating a potentially important role of CYP1B1 in the aetiology of human breast cancer." (PMID 20212917, 2010). "Cyp1b1 was also increased in mammary tumors compared with matched normal mammary glands in the mammary cancer cohort (p < 0.05)." (PMID 20435547, 2010). "Among mammary tumors, Cyp1b1 was elevated substantially by maternal TCDD exposure relative to vehicle (p < 0.05)." (PMID 20435547, 2010). "Maternal TCDD also substantially increased Cyp1b1 expression in mammary tumors, suggesting that changes in mammary progenitor cells resulted in increased Cyp1b1 that persisted through their expansion to tumors." (PMID 20435547, 2010). "The expression level of CYP1B1 in breast carcinomas was up-regulated significantly, providing a new therapy target and phenotype biomarker." (PMID 19638242, 2009). "Another miRNA whose binding sites are underrepresented on eIF4E responsive mRNAs is miR-27b that is often decreased in breast cancer tissues and functions as a negative regulator of CYP1B1, a protein whose genotype correlates with prostate cancer risk." (PMID 19290046, 2009).
breast carcinoma (continued). "Our study was designed to evaluate the hypothesis that the CYP1B1 Val432Leu polymorphisms in the CYP1B1 gene, a key candidate gene involved in phase I hydroxylation of estrogens (17β-estradiol and estrone) to 4-hydroxy catechols might contribute to breast cancer risk in Nigerian women." (PMID 19208203, 2009). "Several studies highlighted the role of XME gene polymorphisms such as CYP1A1, CYP1B1, CYP2D6, mEH, GSTT1, GSTM1 and NAT1 in treatment efficacy as well as survival after treatment of breast carcinoma." (PMID 18423013, 2008). "We also examined tumour protein expression of CYP1B1, because this protein provides a new target for the suppression of tumour growth, as it is overexpressed in many human cancers, including breast cancer." (PMID 18797454, 2008). "The aim of the present study was to analyze the associations between genetic polymorphisms in three estrogen metabolizing enzymes (COMT, CYP1A1, CYP1B1) and the two estrogen receptors (ESR1, ESR2) and the risk of developing breast cancer among women with BBD." (PMID 16808847, 2006). "No study has examined the associations of polymorphisms in CYP1A1, CYP1B1, and COMT with breast cancer risk among women with BBD." (PMID 16808847, 2006). "Moreover, quercetin and glabrol, the components of Glycyrrhiza glabra, not only showed selective inhibition of CYP1B1 in breast cancer cells but also were able to reverse cisplatin resistance in CYP1B1 overexpressing MDA-MB-468 (TNBC) cells." (PMID 40807256, 2025). "As a potential therapeutic target, the knockdown of CYP1B1 could increase the sensitivity of breast cancer cells to paclitaxel, 5-fluorouracil, and cisplatin." (PMID 40989158, 2025). "Similarly, increased expression of CYP1A1 and CYP1B1 in MCF7 breast cancer cells as a result of treatment with methoxylated flavones, eupatorine, and cirsiliol was observed." (PMID 40807256, 2025). "Finally, T47D cells are a cancer cell line notably expressing AHR that activates CYP1A1 and CYP1B1 expression and many downstream genes frequently found in breast cancers." (PMID 41336283, 2025). "Metformin may act as an inhibitor of AhR and its downstream genes, as it reduces expression of CYP1A1 and CYP1B1 in MCF-7 breast cancer cells by suppressing the AhR signaling pathway." (PMID 41440753, 2025). "Data shows negative association of CYP1B1 with doxorubicin based chemotherapy induced N-HEM toxicity including mucositis andperipheral neuropathy in paclitaxel based chemotherapy in breast cancer patients of the selected population." (PMID 40092865, 2024). "Increasing evidence has illustrated that inhibiting the formation of 4-OH-E2 by binding to a CYP1B1 activity site or the CYP1B1-catalyzed enzymes might be a pivotal mechanism of AG in alleviating breast cancer." (PMID 37920216, 2023). "NUPR1 could also active autophagy and bind to the promoter regions of some autophagy-related genes, such as BECN1, GREB1, RAB31, PGR, CYP1B1, thereby regulating breast cancer metastasis and transcription." (PMID 37626099, 2023). "Mechanistically, LNC942 directly recruits METTL14 protein by harboring the specific recognize sequence (+ 176- + 265), thereby stabilizing the CXCR4 and CYP1B1 mRNA in an m6A modification dependent manner thus finally promoting cell proliferation and colony formation of breast cancer cells." (PMID 37365581, 2023). "Human cytochrome P450 1B1 (CYP1B1)-mediated biotransformation of endogenous estrogens and environmental carcinogens promotes the progression of multiple hormone-dependent tumors, including breast cancer." (PMID 36611922, 2022). "Kaplan-Meier analysis demonstrated that breast cancer patients with high CYP1B1 expression had decreased probability of overall survival and disease-free survival than those with low CYP1B1 expression." (PMID 36077068, 2022). "As the role of CYP1B1 in breast cancer was still unknown, we first explored the effect of CYP1B1 on breast cancer cells proliferation, migration and invasion." (PMID 36085146, 2022).
breast carcinoma (continued). "Colony assays identified that CYP1B1 also improved breast cancer proliferation." (PMID 36428734, 2022). "In addition, immunohistochemistry confirmed that CYP1B1 was highly expressed in breast cancer tissues, indicating that CYP1B1 plays an oncogenic role on breast cancer progression." (PMID 36085146, 2022). "Furthermore, the metabolism of quercetin by the CYP1 enzyme, particularly CYP1A1 and CYP1B1, intensifies their antiproliferative effects in breast cancer cells." (PMID 36118099, 2022). "We then hypothesized that CYP1B1 could be responsive for the effects of ZNF276 on the malignant phenotypes of breast cancer cells." (PMID 36085146, 2022). "Breast cancer CYP1B1 elevation is reported for RNA and protein, suggesting that CYP1B1 may play a role in the initiation and/or progression of this cancer." (PMID 36077068, 2022). "Breast cancer samples were divided into tertiles by CYP1B1 RNA levels: low, medium, and high." (PMID 36077068, 2022). "CYP1B1 is the most frequently expressed gene in breast cancer among the CYP1 family members." (PMID 33809117, 2021). "CYP1B1 signaling axis through m6A-dependent regulation in breast cancer cells and tissues." (PMID 34743750, 2021). "Cytochrome P450 1B1 (CYP1B1) is reported to elevate in breast cancer and prostate cancer." (PMID 34257529, 2021). "Additionally, CYP1B1 converts melatonin into N-acetylserotonin which then activates tyrosine receptor kinase B (TrkB), eventually leading to breast cancer cell survival and migration." (PMID 33185690, 2020). "The mRNA and protein levels of the AhR and CYP1B1 are higher in inflammatory breast cancer tissues." (PMID 33185690, 2020). "Women homozygous for the wild-type allele of CYP1B1 were at a statistically significantly decreased acrylamide-associated risk of ER+ breast cancer, while women with at least 1 variant allele were not." (PMID 29445914, 2019). "Among the results for 57 SNPs and 2 gene deletions, rs1056827 in CYP1B1, rs2959008 and rs7173655 in CYP11A1, the GSTT1 gene deletion, and rs1052133 in hOGG1 showed a statistically significant interaction with acrylamide intake for ER+ breast cancer risk." (PMID 29445914, 2019). "The interaction with SNPs in CYP1B1 and CYP11A1 suggests that acrylamide may influence ER+ breast cancer risk through sex hormone pathways." (PMID 29445914, 2019). "CYP1B1 is also a marker for the prevention of certain cancers, such as breast cancer." (PMID 31775380, 2019). "However, the role of PPARα in the regulation of CYP1B1 expression in breast cancer cells has been unclear." (PMID 31775380, 2019). "Nevertheless, since biotransformation of tamoxifen, a widely used drug in breast cancer treatment, occurs via CYP1B1, the mis-expression of CYP1B1 in breast cancer cells due to miR-27b could influence the efficacy of tamoxifen." (PMID 35582590, 2019). "This trend was in line with previous reports documenting that constitutively active AHR in rodent and human mammary tumors associated with elevated CYP1B1, but not CYP1A1 or mRNA." (PMID 31652854, 2019). "To test our hypothesis, we initially investigated the constitutive expression of AhR and its regulated genes, CYP1A1 and CYP1B1 in different breast cancer cell lines." (PMID 28103884, 2017). "In addition, CYP1B1 has been suggested to play an essential role in the development of various hormone-dependent tumors, including breast cancer, through the bio-transformation of endogenous estrogens and environmental carcinogens." (PMID 29290975, 2017). "Collectively, our findings suggest that GPER may be included among the transduction mediators involved by estrogens in the regulation of CYP1B1 toward the development of breast cancer at both primary and metastatic sites." (PMID 29290975, 2017). "Interestingly, overexpression of CYP1B1 leads to the metabolism/biotransformation of docetaxel in in vitro models of breast cancer and of flutamide, commonly prescribed in prostate cancer; resulting in acquired chemotherapeutic resistance." (PMID 27111221, 2016).